KNG1 (kininogen 1)
Diseases named in the same sentence as KNG1 in open-access papers (continued):
Sharing a sentence is not in itself a finding about the gene and the disease.
glioma (continued). "The results confirmed that LINC01018 overexpression not only inhibited the growth of glioma cells but also downregulated miR‐942‐5p expression and upregulated KNG1 expression, while LINC01018 knockdown and miR‐942‐5p mimic did the opposite." (PMID 36550594, 2023). "The levels of KNG1, miR‐942‐5p, and miR‐455‐5p in cancer lesions and adjacent normal samples from glioma patients were then evaluated." (PMID 36550594, 2023). "The purpose of this study was to seek the potential lncRNA and miRNA that regulate KNG1 to affect the development of glioma." (PMID 36550594, 2023). "Inhibition of PI3k/AKT functional activity has been observed after overexpression of KNG1 in glioma cells." (PMID 35109816, 2022). "Kininogen-1/bradykinin stimulates glioma cell migration; the kininogen-activating enzyme kallikrein, was present in all glioblastoma samples." (PMID 35659255, 2022). "Further, the study revealed that overexpression of KNG1 promotes apoptosis and G1 phase cell cycle arrest which demonstrates its role in inhibiting tumor growth in glioma cells." (PMID 35109816, 2022). "KNG1 has been revealed to exert blood coagulation and important anti-inflammatory functions and inhibit the proliferation of endothelial cells and glioma cells." (PMID 35401213, 2022). "Overexpression of KNG1 has been shown to enhance glioma cell death and G1 cell cycle arrest, as well as limit glioma cell viability and angiogenesis." (PMID 35655917, 2022). "The effect of KNG1 on the glioma is rarely reported, so our purpose in to explore its mechanism in glioma cells." (PMID 30068373, 2018). "Overall survival analysis for glioma patients revealed that glioma patients with a high KNG1 expression had a longer survival time than those with a low KNG1 level (high expression vs low expression, log-rank P < 0.05)." (PMID 30068373, 2018). "In the current study, the KNG1 expression level was also significantly reduced in the glioma cells, especially in U87-MG and SHG-44 cells." (PMID 30068373, 2018). "In our study, 404 of 1591 down-regulated DEGs were identified by TGCA and finally the KNG1 was identified as the core gene of glioma patients." (PMID 30068373, 2018). "To explore the effect of KNG1 expression on glioma cell proliferation, we constructed over-expressed KNG1 vector to enforce its expression." (PMID 30068373, 2018). "Overexpression of KNG1 suppresses glioma progression by inhibiting the proliferation and promoting apoptosis of glioma cells, providing a therapeutic strategy for the malignant glioma." (PMID 30068373, 2018). "The KEGG analysis showed that the PI3K/Akt pathway was involved in the regulation of KNG1 on the glioma cells." (PMID 30068373, 2018). "The qPCR results showed that KNG1 expression was obviously reduced in the serums of glioma patients compared with those of normal patients." (PMID 30068373, 2018). "Our study further demonstrated that ADORA1 inhibition promoted glioma apoptosis induced by KNG1." (PMID 40376586, 2025). "We further demonstrated that ADORA1 induces glioma progression by inhibiting KNG1." (PMID 40376586, 2025). "Recently, low expression of KNG1 has been found in the serum of glioma patients." (PMID 36550594, 2023). "Recently, low expression of KNG1 has been found in the serums of glioma patients." (PMID 36550594, 2023). "KNG1 was silenced or overexpressed in T98G and LN‐229 cells to determine its function in glioma." (PMID 36550594, 2023). "Our previous research also proved that KNG1 overexpression could inhibit proliferation and induce apoptosis in glioma cells." (PMID 36550594, 2023). "Therefore, fathoming out the upstream lncRNA of miR‐942‐5p is conducive to further understanding the mechanism of miR‐942‐5p/KNG1 axis in glioma." (PMID 36550594, 2023). "Nonetheless, whether the effect of KNG1 on glioma is achieved via targeting a certain miRNA is yet to be investigated." (PMID 36550594, 2023). "Overexpression of the KNG1 inhibited proliferation and induces apoptosis of glioma cells." (PMID 36785669, 2023).
glioma (continued). "Furthermore, there are no reports concerning the insights into the action mechanism of KNG1 in glioma." (PMID 36550594, 2023). "In a word, the results in this study authenticated that LINC01018 overexpression could inhibit the proliferation, migration, and invasion of glioma cells and the growth of glioma in nude mice by targeting the miR‐942‐5p/KNG1 axis." (PMID 36550594, 2023). "Consistently, we found that KNG1 was lowly expressed in glioma tissues and cells." (PMID 36550594, 2023). "The lncRNA which targeted miR‐942‐5p/KNG1 axis and functioned in glioma was verified." (PMID 36550594, 2023). "Considering that microRNAs (miRNAs) could specifically target a certain mRNA to affect the pathogenesis of various diseases, we wondered whether KNG1 could be regulated by some miRNAs and thereby further affects the progression of glioma." (PMID 36550594, 2023). "LINC01018/miR‐942‐5p/KNG1 pathway regulates the development of glioma cells in vitro and in vivo." (PMID 36550594, 2023). "Nevertheless, whether KNG1 is also targeted by an lncRNA/miRNA axis to influence glioma remains unclear." (PMID 36550594, 2023). "The results of immunohistochemistry unveiled low expression of KNG1 in glioma samples." (PMID 36550594, 2023). "MiR‐942‐5p was highly expressed, whereas KNG1 was lowly expressed in glioma." (PMID 36550594, 2023). "The other hub gene KNG1 (Kininogen-1) is expressed at low level in glioma cells." (PMID 36785669, 2023). "Overexpression of KNG1 could inhibit cell viability and angiogenesis and promote the apoptosis and G1 phase cell cycle arrest of glioma cells." (PMID 32090070, 2020). "Nevertheless, the effect of KNG1 on the glioma is rarely known and our purpose is to explore whether KNG1 can play a role in glioma." (PMID 30068373, 2018). "The results suggested that KNG1 overexpression can exert anti-angiogenesis effect in glioma cells." (PMID 30068373, 2018). "KNG1 was identified as the core gene and lowly expressed in the glioma cells." (PMID 30068373, 2018). "To explore the effects of KNG1 on glioma growth, we established a xenograft nude mouse model." (PMID 30068373, 2018). "And the up-regulation of KNG1 significantly suppressed the expression of XIAP and increased the apoptosis in vivo, suggesting overexpression of KNG1 could promote the apoptosis of glioma cells." (PMID 30068373, 2018). "Overexpression of KNG1 promoted the apoptosis and G1 phase cell cycle arrest of glioma cells." (PMID 30068373, 2018). "We found that up-regulation of the KNG1 evidently increased the apoptosis of glioma cells." (PMID 30068373, 2018). "Overexpression of KNG1 inhibited cell viability and angiogenesis of glioma cells." (PMID 30068373, 2018). "Besides, overexpression of KNG1 suppresses glioma progression by inhibiting the cell viability and promoting apoptosis of glioma cells." (PMID 30068373, 2018). "Meanwhile, the serum KNG1 expression was low in the glioma patients compared to the normal persons." (PMID 30068373, 2018). "Furthermore, ADORA1 inhibition facilitated glioma apoptosis by augmenting kininogen-1 (KNG1)." (PMID 40376586, 2025). "Therefore, further studies of miRNAs that target KNG1 may provide new markers for the diagnosis and treatment of glioma." (PMID 36550594, 2023). "Besides, the effects of miR‐942‐5p mimic and inhibitor could be reversed by KNG1 overexpression and knockdown, respectively, which unearthed that miR‐942‐5p regulated the malignant biological activities of glioma cells by targeting KNG1." (PMID 36550594, 2023). "In addition, our previous research also proved that KNG1 overexpression could inhibit proliferation and induce apoptosis in glioma cells." (PMID 36550594, 2023). "However, the deep mechanism of KNG1 in glioma still awaits further discovery." (PMID 36550594, 2023).
glioma (continued). "In our study, the expressions of cyclinD1, ki67 and XIAP were obviously reduced by the overexpression of KNG1; while the expressions of caspase-3 and caspase-9 were increased, suggesting the up-regulation of KNG1 could exert pro-apoptotic property in glioma cells." (PMID 30068373, 2018). "Subsequent CD31 immunofluorescence staining indicated an enhancement in vascular density in glioma tissues post-ADORA1 overexpression; however, a reduction in vascular abundance was observed when both ADORA1 and KNG1 were overexpressed concurrently." (PMID 40376586, 2025). "The immunohistochemical analysis revealed an increase in the proportion of ki67-positive cells in glioma tissues within the ADORA1 overexpression group, while the ki67 positivity rate diminished following KNG1 overexpression." (PMID 40376586, 2025). "Western blot analysis revealed that elevated ADORA1 expression reduced KNG1 expression in GBM-Z1 and U87 glioma cells." (PMID 40376586, 2025). "Besides, overexpressing KNG1 could induce G1 phase cell cycle of glioma cells." (PMID 30068373, 2018). "TMZ is currently the first‐line anti‐glioma drug, and testing LINC01018/miR‐942‐5p/KNG1 in future studies using TMZ‐resistant/sensitive cells may also provide new evidence for the clinical application of this pathway." (PMID 36550594, 2023). "Additionally, six targets are regulated by our miRNAs both in glioma and meningioma: CR2, KNG1, PROS1, F9, MBL2 and F11, while different miRNAs are dysregulated in each cancer type." (PMID 32545233, 2020).
diabetes (12 papers, 2010 to 2025). "Regardless of diabetes and its remission, we found three proteins (KNG1, ITIH2, and APCS) whose abundance changed after 6 months of bariatric surgery when considering all patients as a whole." (PMID 34501327, 2021).
glioblastoma (10 papers, 2013 to 2025). The most malignant astrocytic tumor (WHO grade IV). "Gn-RH agonist zoladex (goserelin acetate), the first peptide-based antitumor drug approved by the Food and Drug Administration (FDA), decreases U-373MG/U-87MG/LN229 glioblastoma cell proliferation and increases kininogen 1 expression." (PMID 39063232, 2024). "For example, kng1 (kininogen 1) demonstrated tumor suppression and anti-angiogenic properties in glioblastoma." (PMID 31703616, 2019). "Kininogen-1 (KNG1) is associated with tumor suppression and antiangiogenic activity in glioblastoma." (PMID 29552328, 2018). "Likewise, IGF-1, IGFBP2, SPARCL1, kininogen-1, osteopontin, and GRP78 are known to be secreted by glioblastoma cells." (PMID 35659255, 2022). "Our results show that the mRNA transcripts of KNG-1 and KLK-1 are readily detected in SK-N-MC neuroepithelioma cells, rather than in U87-MG glioblastoma cells." (PMID 39684791, 2024).
ovarian carcinoma (9 papers, 2010 to 2025). A malignant neoplasm originating from the surface ovarian epithelium. "Previous studies have shown lower levels of KNG1 in urine or sera of ovarian carcinoma cases and cervical cancer patients respectively." (PMID 28344541, 2017). "For example, significantly reduced levels of kininogen-1 have been detected in the urine of patients with ovarian carcinoma compared with control subjects." (PMID 23894665, 2013). "Previous studies have described the presence of KNG1 and CCKAR as biomarkers of various types of cancer, such as thyroid cancer, liver cancer, ovarian cancer, and cholangiocarcinoma." (PMID 34512870, 2021). "The proteomic profiling of urine samples demonstrated reduced levels of CD59, kininogen-1 and a 39 kDa ITIH4 fragment, as well as the enhanced excretion of a 19 kDa fragment of albumin in patients with ovarian carcinoma compared to control women." (PMID 21083881, 2010). "When taken as overall, the levels of CD59, kininogen-1 and ITIH4 fragment were significantly lower in ovarian carcinoma patients by 3.6-, 2.5- and 1.9-folds, respectively, compared to those excreted by the control subjects." (PMID 21083881, 2010). "In case of the 19 kDa albumin fragment, interaction appeared to be detected only in the pooled urine of patients with ovarian carcinoma compared to that of the controls, while the inverse was observed for CD59, kininogen-1 and the 39 kDa fragment of ITIH4." (PMID 21083881, 2010). "KNG1 and ITIH4 were reported to be significantly downregulated in ovarian cancer." (PMID 35109816, 2022). "Moreover, other studies showed altered urinary levels of KNG1 in endometriosis, and of ALBU e ITIH4 in ovarian carcinoma." (PMID 33923220, 2021). "In the present proteomic profiling study, the significant reduced excretion of CD59, kininogen-1 and a 39 kDa fragment of ITIH4, and the enhanced levels of a 19 kDa fragment of albumin were detected in the urine samples of patients with ovarian carcinoma relative to those of the control subjects." (PMID 21083881, 2010). "In view of these previous reports, it was not surprising to find similar reduced levels of kininogen-1 in the urine of patients with ovarian carcinoma in this study." (PMID 21083881, 2010). "The different altered levels of CD59, kininogen-1 and fragments of ITIH4 and albumin in the urine of patients with ovarian carcinoma, relative to the controls, was confirmed when their 2-DE urine protein profiles were subjected to image analysis using the Image Master 2 D Platinum Software 7.0." (PMID 21083881, 2010). "Significant reduced levels of CD59, kininogen-1 and a 39 kDa fragment of inter-alpha-trypsin inhibitor heavy chain H4 (ITIH4), and enhanced excretion of a 19 kDa fragment of albumin, were detected in the urine of patients with ovarian carcinoma compared to the control subjects." (PMID 21083881, 2010). "CD59, kininogen-1 and fragments of ITIH4 and albumin may be used as complementary biomarkers in the development of new noninvasive protocols for diagnosis and screening of ovarian carcinoma." (PMID 21083881, 2010).
Obesity (8 papers, 2019 to 2025). Accumulation of substantial excess body fat. "Weight loss following very low calorie diets increased plasma KNG1, in accordance with the increase observed in our patients following obesity surgery." (PMID 34501327, 2021). "Alternatively, high levels of KNG1 in the MUHO group may be the result of an adaptive response to counter the impaired metabolism in adipose tissue in individuals with severe obesity." (PMID 31623319, 2019). "In the mouse samples, it is particularly noteworthy that the sEVs derived KNG1 protein level in sEVs exhibited a significant upregulation of 5.65-fold, followed by a 2.63-fold upregulation in the ECM1 protein level under obesity conditions." (PMID 38402239, 2024). "The following seven proteins are present in higher amounts in the Obesity group compared with the Control group: hemopexin—HPX, complement factor B—CFB, complement C3—C3, kininogen-1—KNG1, vitronectin—VTN, pigment epithelium-derived factor—SERPINF1 and beta-Ala-His dipeptidase—CNDP1." (PMID 41441338, 2025). "The MRM data validated a significant elevation of ECM1, but not KNG1, in the sEVs of human subjects with obesity or overweight." (PMID 38402239, 2024). "Notably, CPN2 (carboxypeptidase N Subunit 2), F5 (coagulation factor V), ECM1 (extracellular matrix protein 1), KNG1 (kininogen 1), FN1 (fibronectin 1), and GPLD1 (glycosylphosphatidylinositol-specific phospholipase D1) were found to be elevated in both human and mouse sEVs under obesity conditions." (PMID 38402239, 2024).
thrombosis (8 papers, 2015 to 2025). "Applying this original concept helped to identify two candidate SNPs in the KNG1 gene susceptible to have an important role in the genetic regulation of the coagulation pathway as a whole and consequently of thrombosis disease." (PMID 28005926, 2016). "Notably, this variant was identified in an individual with high FXI levels from the GAIT-2 Project, so the new putative pathogenic mutation NM_001102416.2: c.758-12T>C in the KNG1 was genotyped in the case-control study of thrombosis." (PMID 28445521, 2017). "Similar to FXII deficient mice, Kng1−/− mice displayed a significantly prolonged time to carotid artery occlusion following Rose Bengal administration and laser-induced arterial injury, suggesting that plasma HK contributes to arterial thrombosis in mice." (PMID 25949215, 2015). "Elevated plasma levels of FXI have been correlated with venous thrombosis and ischemic stroke; therefore, KNG1 could be involved in the pathogenesis of SVO stroke via regulation of plasma FXI levels." (PMID 29123153, 2017).
Hypertension (7 papers, 2015 to 2026). The presence of chronic increased pressure in the systemic arterial system. "In conclusion, hypertension altered processes related to central nervous system development, inflammation and blood coagulation (including YKL-40, KNG1, DAG1, and the SERPIN family)." (PMID 41152331, 2025).
liver cancer (7 papers, 2013 to 2022). An epithelial or non-epithelial malignant neoplasm that arises from the liver. "The degree of liver function impairment in patients with liver cancer is generally severe, and the KNG1 level is also low." (PMID 35935258, 2022). "In addition, if a patient is found to be positive for kininogen-1 and CEA, yet negative for alpha fetal protein, then it is possible he/she suffers from CRC rather than liver cancer." (PMID 23894665, 2013).
Stroke (7 papers, 2009 to 2025). Sudden impairment of blood flow to a part of the brain due to occlusion or rupture of an artery to the brain. "KNG1 not only plays a central role in coagulation and thrombosis but is also significantly associated with cryptogenic young stroke." (PMID 36959823, 2023). "A study conducted in mice recognized KNG1 as a key mediator of ischemic neurodegeneration and neuronal damage by increasing microvascular thrombosis, blood–brain barrier leakage and inflammation; KNG1 inhibition allowed to protect from thromboembolic disorders and stroke." (PMID 30244532, 2018).
diabetic nephropathy (6 papers, 2020 to 2022). "In the context of our result, decreased kininogen-1 in pregnant women T1DM may indicate a higher risk of developing diabetic nephropathy with microalbuminuria, which is associated with maternal and fetal complications." (PMID 35610262, 2022). "Under expression of PTPRO and KNG1 with fold change of -3.308 and -1.618 respectively were reported in diabetic nephropathy in comparison with healthy living donors." (PMID 34557161, 2021). "According to previous studies, kininogen-1 has some utility in predicting microalbuminuria and diabetic nephropathy in patients with T1DM and T2DM, however, its utility as a biomarker in T1DM disease progression in pregnancy requires further clinical evaluation." (PMID 35610262, 2022). "Kininogen-1 plays a role in the kallikrein-kinin system (cooperating with the renin-angiotensin system); it has been suggested as a possible urinary biomarker for diabetic nephropathy and may effect renal protection." (PMID 34248840, 2021).
breast carcinoma (5 papers, 2009 to 2023). "Previous studies performed on serum and plasma samples have shown that the expression of kininogen-1 was significantly reduced in patients with gastrointestinal cancer, breast cancer and two different types of cervical cancer." (PMID 21083881, 2010). "In addition, several other studies have shown a significant reduction of the KNG1 level in serum and plasma samples in patients with gastrointestinal cancer, breast cancer and cervical cancer." (PMID 37371512, 2023).
cervical cancer (5 papers, 2010 to 2023). A primary or metastatic malignant neoplasm involving the cervix. "On the contrary, in previous reports, lowered expression of KNG1 was detected in various types of cancers including gastrointestinal, breast and cervical cancers, which has been attributed to its contribution to the survival of cancer cells." (PMID 23849470, 2013).
prostate carcinoma (5 papers, 2013 to 2021). A carcinoma that arises from epithelial cells of the prostate gland. "Our study first described the upregulation of KNG1 and CCKAR in prostate cancer." (PMID 34512870, 2021).